XIST (X inactive specific transcript)
Diseases named in the same sentence as XIST in open-access papers (continued):
Sharing a sentence is not in itself a finding about the gene and the disease.
breast cancer (continued). "Due to these functions of XIST in BRCA in public databases, we selected 98 breast cancer samples to assess its clinicopathological role." (PMID 36212008, 2022). "Among these five lncRNAs, the XIST (p = 9.2e−12), NORAD (p = 1.1e−9), and OIP5-AS1 lncRNAs (p = 8.3e−11) were expressed differentially in breast cancer." (PMID 36312586, 2022). "LncRNA NEAT1 as a significantly dysregulated RNA in the breast cancer and gastric cancer patients have significant interactions with the hub coding (MTRNR2L8) and non-coding RNAs (lncRNA XIST and hsa-miR-612)." (PMID 35581633, 2022). "High expression of XIST can be used to identify BRCA1-like breast cancer and has a worse prognosis than BRCA1-like breast cancer patients with low expression of XIST." (PMID 36035993, 2022). "A few lncRNAs have been found to regulate miR-424-5p in various cancer cells, including LINC00922 in breast cancer, CDNK2B-AS1 in hepatocellular carcinoma, and XIST in neuroendocrine tumors." (PMID 33477683, 2021). "We searched the search interface for the survival of XIST and PUSL1 in GSE42568 (breast cancer expression profile) and found that the HR value of XIST was <1, while the Cox p-value was less than 0.05." (PMID 34113575, 2021). "Functionally, XIST induced sponging of miR-125b-5p and removed the inhibitory effect of this miRNA on NLRC5, a breast cancer promotor, thus promoting the malignancy of breast cancer cells." (PMID 34527584, 2021). "Moreover, expression levels of XIST have been correlated with patients’ survival in different kinds of cancers including bladder cancer, esophageal squamous cell carcinoma, nasopharyngeal carcinoma, lung cancer, gastric cancer, colorectal cancer and breast cancer." (PMID 34179019, 2021). "LncRNAs XIST, TSIX, GATA3-AS1 and LINK-A play an oncogenic role in tumor progression and immune evasion in breast cancer and are all notably upregulated in breast cancer tissues, which is related to the expression of PD-L1." (PMID 34496886, 2021). "The authors also found that XIST sponged miR-155, which in turn upregulated the expression of caudal-type homeobox 1 (CDX1) and inhibited the progression of breast cancer." (PMID 34527584, 2021). "XIST and TSIX are overexpressed in the lymph nodes, and different body fluids of breast cancer patients but differentially expressed in patients with different breast cancer subtypes." (PMID 34496886, 2021). "Our study characterizes the regulation of XIST by miR-7 and provides evidence that overexpression of miR-7 or downregulation of XIST underlies the attenuation of properties of BCSCs and the decrease of the BCSC subset, which may be a potential strategy for breast cancer therapy." (PMID 32143670, 2020). "The findings from this study uncover the molecular mechanisms by which miR-7 inhibits XIST, modulates the miR-92b/Slug/ESA axis, and decreases the RELA and CD44 expression, resulting in a reduced BCSC subset and breast cancer growth inhibition." (PMID 32143670, 2020). "XIST and TSIX are two long non-coding (lnc)RNAs possessing a role in X chromosome inactivation (XCI) as well as in breast cancer (BC)." (PMID 31998636, 2019). "For example, KCNQ1OT1, MALAT1, XIST, and NEAT1 are experimentally confirmed breast cancer-related lncRNAs, which have been ranked 2nd, 11th, 12th, and 19th in the predicted list based on the model of DCSLDA, respectively." (PMID 30046354, 2018). "We found two breast cancer-related lncRNAs, MALAT1 and XIST, were significantly and differentially co-expressed with mRNAs (ALG14, TOX4, and C12orf32) in tumor and normal breast tissue via trans-acting mechanism." (PMID 27597120, 2016). "For example, XIST, KCNQ1OT1 and NEAT1 are there experimentally confirmed breast cancer related lncRNAs, which have been ranked 1st, 8th, and 12th in the predicted list based on the model of HGLDA, respectively." (PMID 26278472, 2015).
breast cancer (continued). "However, our data contrast with findings in breast cancer cell lines, where doxycycline (DOX)-induced XIST KD increases E-CSCs." (PMID 39546568, 2024). "The XIST lncRNA could inhibit cancer proliferation and ETM and promote apoptosis in breast cancer, as affirmed by a previous study." (PMID 36312586, 2022). "Our study determined the lncRNA XIST/miR-92b-3p/MTF1 regulatory axis for breast cancer, which has not been studied before." (PMID 36312586, 2022). "We identified the lncRNA XIST/miR-92b-3p/MTF1 regulatory axis for breast cancer, which has not been studied before." (PMID 36312586, 2022). "Also, we suggest that the expression level of XIST and MT-RNR2 in the human breast cancer and GC patients to evaluate the accurate expression pattern of these gene and lncRNA in the patients." (PMID 35581633, 2022). "We discovered the lncRNA XIST/miR-92b-3p/MTF1 regulatory axis for breast cancer, which has not yet been investigated previously." (PMID 36312586, 2022). "We found that in the regulatory network, miR-301a-3p, miR-93-5p, miR-454-3p, miR-181b-5p, XIST, LINC00472, MIR31HG, MEG3, MIR155HG, and LINC00667 have been reported in breast cancer." (PMID 34220926, 2021). "Furthermore, lncRNAs XIST and TSIX were markedly increased in the tissues, lymph nodes, and different body fluids of breast cancer patients compared to controls." (PMID 31998636, 2019). "Additionally, we previously reported decreased XIST and AUTS2 mRNA expression in breast cancer cells as a result of forced ACSL4 expression." (PMID 26636648, 2015). "Likewise, decreased expression levels of FGF14 antisense RNA 2 (FGF14‐AS2), X inactive specific transcript (XIST), BC040587, and MEG3 in breast cancer tissue and cell lines compared with corresponding normal control were associated with unfavorable survival in breast cancer." (PMID 36274054, 2023). "To further substantiate the role of XIST in regulating tumor growth and CSC activity, we implanted SUM159-shXIST cells with stable expression of firefly luciferase into NOD/SCID mice and monitored mammary tumor growth by bioluminescence imaging in mice fed with or without DOX-containing water." (PMID 36922677, 2023). "Importantly, expressions of exosomal XIST were extracted from serum before the resection of tumours in breast cancer patients and analysed to compare the relapses or not by using scatter plots." (PMID 33949761, 2021). "Interestingly, evidence of XIST and another protein 53BP1, have been reported as potential predictive markers of resistance to high dose alkylating chemotherapy and can be used to identify BRCA1-like breast cancer patients." (PMID 29732012, 2018). "To verify the hypothesis that the lack of functional BRCA1 is involved in the inappropriate expression of XIST from Xa, we performed BRCA1 silencing in HMEC (XCI-type 0) and in the following BRCA1wt breast cancer cell lines: MDA MB 231(XCI-type 1), T47D (XCI-type 1) and MCF7 (XCI-type 2)." (PMID 19440381, 2009). "It has been proven that XIST is up-regulated in many tumors, including glioblastoma, hepatocellular carcinoma (HCC), breast cancer (BC), NSCLC, as well as nasopharyngeal carcinoma (NPC), which suggests that it can become a valuable diagnostic biomarker specific for this group of diseases." (PMID 34204634, 2021). "Indeed, the positive effect of BRCA1 deficit on Xa XIST expression is demonstrated in vitro by BRCA1 silencing in XCI-type 2 (Xi negative/XIST positive) MCF7 breast cancer cell line, which leads to a significant increase of XIST levels and promoter demethylation." (PMID 19440381, 2009). "We provide evidence that in breast cancer cells BRCA1 is involved in XIST regulation on the active X chromosome, but not in its localization as previously suggested, and that XIST can be unusually expressed by an active X and can decorate it." (PMID 19440381, 2009).
breast cancer (continued). "In contrast to miR-7 expression, the relative expression levels of XIST, RELA, CD44, slug, and ESA were significantly higher in breast cancer tissues than in adjacent noncancerous tissues (p = 0.0486, p = 0.038, p = 0.0297, p = 0.0420, and p = 0.0434, respectively)." (PMID 32143670, 2020).
colorectal cancer (60 papers, 2012 to 2025). A primary or metastatic malignant neoplasm that affects the colon or rectum. "Loss of METTL14 in human colorectal cancers correlates with high levels of XIST and poor patient survival." (PMID 33564819, 2021). "In the present research, in order to determine if XIST modulates the activities of colorectal cancer by HIF‐1A/AXL signaling, the expression of AXL after loss‐ and gain‐of‐function of XIST was detected in colorectal cancer cells." (PMID 32061057, 2020). "In response to miR-93-5p, XIST adjusts the expression of HIF-1A and promotes the EMT process, proliferation and migration and tumorigenesis of colorectal cancer, suggesting that XIST may serve as a diagnostic and therapeutically relevant marker." (PMID 39830506, 2024). "Next, we took the XIST gene as an example for further analysis to verify whether it might be associated with Colorectal cancer." (PMID 36595551, 2023). "In conclusion, the XIST/miR‐30a‐5p/ROR1 axis could be deemed as pivotal markers underlying colorectal cancer, and administration of atractylenolide II might improve the chemotherapeutic efficacy for colorectal cancer." (PMID 30907503, 2019). "For instance, METTL14, which is underexpressed in colorectal cancer (CRC) and linked to a poor prognosis, reduces m6A levels on XIST and enhances YTHDF2-mediated XIST expression, thereby inhibiting tumor cell growth." (PMID 40271153, 2025). "XIST acts as a ceRNA for miR-93-5p, promoting colorectal cancer metastasis partially through HIF-1A/AXL signaling." (PMID 40861273, 2025). "The univariable analysis showed that increased levels of CA19-9, XIST, and FOXK1, as well as decreased levels of TSIX and miRNA-497, were linked to a greater risk of colorectal cancer (CRC)." (PMID 40032945, 2025). "Our purpose was to examine the expression pattern and clinical significance of plasma-derived exosomal lncRNAs CCAT1 and lncRNA XIST in colorectal cancer patients." (PMID 40028475, 2025). "Previous studies have pointed out lncRNA XIST was elevated in gastric, glioma, pancreatic, and colorectal cancers." (PMID 38446257, 2024). "Knockout of METTL14 decreased the m6A level of lnc RNA XIST, reduced the recognition and degradation of XIST by YTHDF2, and promoted the expression of XIST and the proliferative capacity of colorectal cancer." (PMID 39289775, 2024). "m6A in LncRNA NEAT1 was shown to exhibit oncogenic function in prostate cancer progression, METTL14-induced m6A process suppressed XIST expression, and suppresses proliferation and metastasis of colorectal cancer." (PMID 37773181, 2023). "The knockdown of METL14 abolishes m6A levels of the downstream target, the lncRNA for XIST, and augments XIST expression, thus promoting the invasive ability of colorectal cancer cells and tumourigenicity." (PMID 35075167, 2022). "METTL14 knockout reduces the m6A level of downstream XIST, which can’t be recognized by YTHDF2 and inhibits its degradation, promotes the expression of XIST, and promotes the progress of colorectal cancer." (PMID 35022030, 2022). "Then, we further performed a literature search and selected 2 miRNAs (miR-342-3p/miR-650) and 2 lncRNAs (NEAT1/XIST) that with related reports in UC or UC-related colorectal cancer." (PMID 36419192, 2022). "For example, XIST expression was upregulated in colorectal cancer, and its downregulation repressed colorectal cancer cell proliferation, migration, and invasion." (PMID 35899235, 2022). "For example, the m6A “writer” METTL14 was reported to inhibit the proliferation and metastasis of colorectal cancer through the downregulation of the oncogenic XIST lncRNA." (PMID 34268304, 2021). "Further, the overexpression and downregulation of XIST led to an increase and a decrease in the growth of colorectal cancer, respectively, in a xenograft model." (PMID 34298879, 2021).
colorectal cancer (continued). "For instance, in colorectal cancer tissue, XIST expression is remarkably overexpressed, and XIST enhances the proliferation of cancer cells by regulating miR-132-3p/MAPK1 axis." (PMID 33942699, 2021). "In colorectal cancer, XIST also augments the level of HIF-1α via negatively regulating miR-93-5p activity; therefore, XIST can possess stimulatory effects on migration, invasion, and the EMT process." (PMID 34298879, 2021). "And miR-137 was suppressed by lncRNA XIST and inhibited 5-FU/cisplatin resistance and glycolysis in colorectal cancer." (PMID 34250246, 2021). "In colorectal cancer, up-regulation of XIST in extracellular vesicles isolated from serum samples had an appropriate diagnostic value [Area under curve (AUC) = 0.86, sensitivity = 0.88 and specificity = 0.90]." (PMID 34179019, 2021). "In the present research, our team demonstrated the upregulation of XIST expression, which was related to tumor progression, and the downregulation of miR‐93‐5p in cells and tissues of colorectal cancer." (PMID 32061057, 2020). "At last, we proved that XIST enhanced the in vivo and in vitro activities of colorectal cancer by regulating AXL signaling." (PMID 32061057, 2020). "Firstly, we determined the expression of miR‐93‐5p and XIST in tissues from patients who suffered from colorectal cancer and also in colorectal cancer cells." (PMID 32061057, 2020). "XIST is a ceRNA for miR‐93‐5p to promote the progression of colorectal cancer partly through HIF‐1A/AXL signaling." (PMID 32061057, 2020). "The content of XIST was notably upregulated in colorectal cancer tissues than that of normal control." (PMID 32061057, 2020). "Here, we report that XIST promotes colorectal cancer tumorigenesis by regulating miR‐93‐5p/HIF‐1A/AXL signaling pathway." (PMID 32061057, 2020). "Tumor metastasis of colorectal cancer was promoted by the acceleration of the XIST/miR-137/EZH2 axis on cell migration and invasion." (PMID 32127028, 2020). "For instance, the overexpressed lncRNA XIST in colorectal cancer promoted cell proliferation and invasiveness through controlling ZEB1 expression by acting as a ceRNA for miR-200b-3p." (PMID 31998636, 2019). "In Glioma, XIST increases Rac-1 signaling by sequestering miR-137, in colorectal cancer, it increases MAPK1 signaling by sequestering miR-132-3p or by sequestering miR378, which targets MAPK1 in prostate." (PMID 30555629, 2018). "The object of our study was to evaluate the differential expression of lncRNAs colon cancer associated transcript 1 (CCAT1) and X-inactive specific transcript (XIST) in plasma exosomes of colorectal cancer (CRC) patients and investigate their potential as clinical biomarkers." (PMID 40028475, 2025). "Furthermore, studies have established that XIST functions as an oncogene in colorectal cancer, with elevated levels of XIST positively correlating with tumor progression." (PMID 40861273, 2025). "Furthermore, lncRNA XIST has been found to facilitate tumor metastasis in colorectal cancer by modulating the miR-137-EZH2 axis." (PMID 39830506, 2024). "XIST modulates via the miR 93-5p the HIF1A-Axl axis in colorectal cancer." (PMID 39639337, 2024). "METTL14 could regulate the m6A level of XIST, and the loss of METTL14 is related to poor prognosis of patients with colorectal cancer." (PMID 36387210, 2022). "On the contrary, as an essential component of m6A writer, METTL14 has been shown to suppress proliferation and metastasis of colorectal cancer by downregulating oncogenic lncRNA XIST, suggesting the regulatory network of m6A and lncRNA in tumor pathophysiology was extremely complicated." (PMID 35615374, 2022). "Other studies showed that ALKBH5 could promote the metastasis and invasion of gastric cancer by demethylating the expression of lncRNA NEAT1 and that METTL14 acts as a prognostic biomarker in colorectal cancer by downregulating oncogenic lncRNA XIST." (PMID 35309906, 2022).
colorectal cancer (continued). "Thus, we propose that miR‐210 regulates the degradation of XIST in cells as a mechanism to promote colorectal cancer and reducing NME1 expression." (PMID 36116139, 2022). "Oncogenic lncRNA XIST is inhibited by METTL14 (writer) in colorectal cancer." (PMID 34238292, 2021). "XIST was reported to exert oncogenic function in colorectal cancer via targeting miR-132-3p." (PMID 34419049, 2021). "Earlier researches showed that XIST can advance the progression of colorectal cancer." (PMID 32061057, 2020). "The inhibitor BGB324 of AXL was used to further detect whether XIST enhances the activities of colorectal cancer by AXL signaling." (PMID 32061057, 2020). "In our research, our team speculated that XIST may accelerate colorectal cancer progression by inhibiting miR‐93‐5p expression." (PMID 32061057, 2020). "Moreover, the in vivo and in vitro potential mechanism of XIST in colorectal cancer development was analyzed." (PMID 32061057, 2020). "Above all, our research showed that XIST is an oncogene of colorectal cancer." (PMID 32061057, 2020). "XIST expression was detected to confirm whether XIST is expressed differently in different colorectal cancer samples." (PMID 32061057, 2020). "This investigation was conducted to elucidate whether atractylenolide II could reverse the role of lncRNA XIST/miR‐30a‐5p/ROR1 axis in modulating chemosensitivity of colorectal cancer cells." (PMID 30907503, 2019). "Consistent with our results, previous studies have found that lncRNA XIST expression was up-regulated in patient with collecting duct carcinoma of the kidney, sporadic human colorectal cancer, and gastric fundus of a male mouse infected with helicobacter felis which can lead to gastric cancer." (PMID 27620004, 2016). "Apart from this, DNA copy number changes of XIST gene was reported in colorectal carcinomas." (PMID 22984562, 2012). "Therefore, XIST could potentially be targeted for therapy and used as a prognostic indicator for colorectal cancer." (PMID 39830506, 2024). "However, some studies showed that XIST promoted growth and invasion of colorectal cancer cells, and silencing XIST could repress chemoresistance of acute myeloid leukemia." (PMID 36212008, 2022). "Hence, the present study renders leading perspective to the molecular actions of XIST in colorectal cancer tumorigenesis, and may advance the process to diagnose lncRNA‐related disease and treatment." (PMID 32061057, 2020). "Using both male and female colorectal cancer samples, Yang demonstrated that XIST is the competitive endogenous RNA of miR93-5p to promote HIF-1 A and then the upregulated AXL level facilitates migration and proliferation of colorectal cancer." (PMID 39639337, 2024). "Either the tumor weight or tumor size was enlarged in mice overexpressing KCNQ1OT1 or XIST, indicating that KCNQ1OT1/XIST overexpression induced tumor growth in mice with colorectal cancer." (PMID 34521445, 2021). "Previous research has shown that HIF‐1 is capable of directly binding to AXL and activating the expression of it; therefore, to further study the mechanisms of XIST, the expression level of AXL in colorectal cancer cells was detected." (PMID 32061057, 2020). "For example, XIST, which is a lncRNA over-expressed in colorectal cancer tissues and cells, can promote invasion, proliferation, and EMT progress through XIST/miR-200b-3p/ZEB1 pathway." (PMID 30823895, 2019). "Our results demonstrated that XIST and ROR1 expressions were dramatically up‐regulated, yet miR‐30a‐5p expression was down‐regulated within colorectal cancer tissues (P < 0.05)." (PMID 30907503, 2019). "In contrast to these hematological cancers, XIST gene copy number amplifications and increased expression levels have been detected in other cancers, e.g., microsatellite-unstable colorectal carcinoma (CRC)." (PMID 29125541, 2017).